RN7SL837P (RNA, 7SL, cytoplasmic 837, pseudogene)
Gene: Miscellaneous RNA gene on chromosome 1 (230,894,141 to 230,894,427, forward strand). Ensembl gene ENSG00000240502.
Homologues: Orthologues: chimpanzee Metazoa_SRP (99% identical), macaque Metazoa_SRP (91% identical). Paralogues in human: RN7SL2 (80% identical), RN7SL1 (79% identical), RN7SL3 (79% identical), RN7SL122P (78% identical), RN7SL220P (78% identical), RN7SL408P (76% identical), RN7SL709P (76% identical), RN7SL798P (76% identical), RN7SL127P (76% identical), RN7SL608P (76% identical), RN7SL60P (76% identical), RN7SL113P (75% identical), and 702 more.